BCL6 (BCL6 transcription repressor)
Diseases named in the same sentence as BCL6 in open-access papers (continued):
Sharing a sentence is not in itself a finding about the gene and the disease.
colon cancer (9 papers, 2012 to 2026). "IL-16 plays a role in promoting cellular inflammation; BCl-6 plays a role in inhibiting apoptosis in colon cancer cells; and NFKBIZ plays a role in promoting the expression of the IL-17 inflammatory signaling pathway." (PMID 36839472, 2023). "On the other hand, it has been shown that DNA hypermethylation in the promoters of miR-124a and miR-127 leads to their transcriptional silencing in colon cancer models and influences the expression of two oncogenes, such as BCL6 and CDK6." (PMID 22277129, 2012). "Additionally, Wang Team demonstrated that IRF4 exerts a negative regulatory effect on BCL6, facilitating Treg cell differentiation into macrophage-like cells and consequently impeding colon cancer cell proliferation." (PMID 39582536, 2024). "Moreover, IRF4 up-regulation ameliorated tumor growth of colon cancer by promoting the transdifferentiation of Tregs into macrophage-like cells through inhibition of BCL6 expression." (PMID 33468159, 2021). "Significantly, BCL6 was also upregulated in CRC tumor samples, and high expression of BCL6 was correlated with poor prognosis of colon cancer patients based on TCGA datasets analysis." (PMID 35906392, 2022). "However, when BCL6 levels in CD8 T cells were analyzed across scRNA-seq datasets from colon cancer samples, we found cytotoxic or effector CD8 T cells had higher expression of BCL6, which is encouraging for studying the distinct gene suppressive function of BCL6 in T-cell responses during cancer." (PMID 41145211, 2026).
rheumatoid arthritis (9 papers, 2012 to 2025). A chronic, systemic autoimmune disorder characterized by inflammation in the synovial membranes and articular surfaces. "Since relatively little is known about the Tfh cells in rheumatoid arthritis (RA) patients, in this study, Tfh-cell frequency, related cytokine IL-21, and transcription factor Bcl-6 were investigated in 53 patients with RA and 31 health controls." (PMID 22649468, 2012). "Compared with the healthy controls, higher expression of Bcl6 and lower Blimp-1 expression in the peripheral blood are observed in patients with rheumatoid arthritis (RA)." (PMID 32766317, 2020). "In addition, in certain inflammatory sites, such as synovium from rheumatoid arthritis patients, non-classic Tfh-like cells have been identified, which are CXCR5low but have high expression levels of Bcl-6, PD-1, and IL-21." (PMID 30410493, 2018).
Hypertension (8 papers, 2015 to 2024). The presence of chronic increased pressure in the systemic arterial system. "The attenuated vascular remodeling caused by BCL6 in hypertension may partially contributes to its antihypertensive effect." (PMID 30805081, 2019). "BCL6 is a sequence-specific transcriptional repressor that shows increased renal expression in young SHR59 but lower expression as hypertension develops in adulthood, as we also observed in vehicle SHR." (PMID 38501595, 2024). "Previous studies revealed that BCL6 is a candidate gene for spontaneous hypertension and stroke, but further investigation into the mechanisms of these genes and ischemic events is necessary." (PMID 35372347, 2022). "The analyses of SHR-specific genes using IPA revealed that B-cell CLL/lymphoma 6 (Bcl6) and SRY (sex determining region Y)-box 2 (Sox2) were possible candidate genes responsible for causing hypertension in SHRs." (PMID 26165378, 2015). "recently reported that BCL6 can lower blood pressure by suppressing vascular smooth muscle cell proliferation, attenuating oxidative stress injury, and microvascular remodeling in the Ang-II induced hypertensive rats." (PMID 36703963, 2022). "We conclude that BCL6 attenuates proliferation and oxidative stress of VSMCs in hypertension." (PMID 30805081, 2019). "BCL6 overexpression attenuates hypertension and inflammation in the renal cortex of SHR." (PMID 29072703, 2017). "Given that prostaglandin is one of arachidonic acid metabolites, our finding suggest Bcl6 might be involved in arachidonic acid pathway, to elicit programmed hypertension." (PMID 25739086, 2015). "B-cell lymphoma 6 (BCL6) is known as a key intervention target for autoimmune diseases by inhibiting production of ROS and apoptosis; however, it is unclear whether this can reduce hypertension." (PMID 36703963, 2022). "Moreover, BCL6 overexpression attenuated vascular remodeling and hypertension in SHR." (PMID 30805081, 2019). "However, it is unknown whether BCL6 plays a role in vascular remodeling in hypertension." (PMID 30805081, 2019). "The IPA path explorer tool revealed that B-cell CLL/lymphoma 6 (Bcl6) and SRY (sex determining region Y)-box 2 (Sox2) were possible candidate genes that trigger hypertension in SHRs." (PMID 26165378, 2015).
lymphoid neoplasm (8 papers, 2017 to 2023). A neoplasm composed of a lymphocytic cell population which is usually malignant (clonal) by molecular genetic and/or immunophenotypic analysis. "According to the recent WHO classification of lymphoid neoplasms (2016), HGBLs with c-Myc, Bcl2, and/or Bcl6 rearrangement were classified as double expressors and/or triple expressors, respectively." (PMID 36312606, 2022). "Moreover, based on the differential expression of MUM-1, BCL6, and CD10, we conclude that most of the lymphoid neoplasms characterized by very large spleens were consistent with DLBCL." (PMID 30687320, 2018). "Our transcriptomic characterization supports the new, 2022 adaptation of WHO nomenclature of lymphoid tumors regarding these classes where MYC/BCL6 rearrangements are not further considered as a hit-classifier and the other two types are now defined as IRF4-R LBCL and HGBL-11q, respectively." (PMID 35884496, 2022).
marginal zone lymphoma (8 papers, 2011 to 2026). A usually indolent mature B-cell lymphoma, arising from the marginal zone of lymphoid tissues. "The molecular characteristics of BN2, such as the NOTCH2 mutation and the BCL6 translocation, are shared by marginal zone lymphoma (MZL) and transformed MZL." (PMID 40507898, 2025). "In addition, for cases with single BCL6-trans signature, the mutations in several genes were also frequently determined in marginal zone lymphoma, including NOTCH2 (14.6%, 6/41), KLF2 (34.1%, 14/41), TNFAIP3 (19.5%, 8/41), and FAS (17.1%, 7/41) mutations." (PMID 32736575, 2020). "BCL6 translocation is recurrently seen in both follicular and marginal zone lymphoma." (PMID 31844144, 2020).
medulloblastoma (8 papers, 2016 to 2024). A malignant, invasive embryonal neoplasm arising from the cerebellum. "For example, Mll4 deletion downregulates tumor suppressor genes (e.g., Bcl6 and Dnmt3a) by generally decreasing the abundance of SEs and H3K4me3 and causing widespread degradation of these epigenomic marks during medulloblastoma generation." (PMID 37501079, 2023). "Mll4 deletion downregulated tumor suppressor genes (Bcl6 and Dnmt3a) in medulloblastoma by decreasing SE function." (PMID 37501079, 2023). "We have shown that KMT2D-activated tumor-suppressive super-enhancers interact with the promoters of the DNA methyltransferase gene Dnmt3a and the medulloblastoma suppressor gene Bcl6 and upregulate these genes to suppress medulloblastoma genesis." (PMID 34194626, 2021). "Further association with mutations of the BCL6 repressor gene BCOR, commonly altered in medulloblastomas, neuroepithelial tumors, and sarcomas, highlights a further avenue for interventional study through its regulation of the SHH pathway." (PMID 28966033, 2017). "BCOR suppresses the tumor progression of SHH medulloblastoma by a BCL6/BCOR/SIRT1 complex that induces epigenetic repression of GLI1 and GLI2." (PMID 27825128, 2016). "In medulloblastoma (MB), BCL6 could lead to epigenetic inhibition of the GLI family zinc finger 1/2 (GLI1 and GLI2), which are the critical effectors of the sonic hedgehog (Shh) pathway." (PMID 37060074, 2023). "In addition, KMT2D activates expression of the tumor suppressor genes Bcl6 and Sirt1, whose proteins repress expression of several oncogenic Notch pathway genes to suppress medulloblastoma." (PMID 34194626, 2021). "In most cases, BCL6 expression is associated with poor prognosis and worse outcome, although not always—BCL6 can suppress tumorigenesis in medulloblastoma and is associated with a better prognosis in a subset of gastric lymphoma." (PMID 32320427, 2020). "As similar mechanism of action, loss of function of KMT2D inhibits tumor suppressor genes DNMT3A and BCL6, upregulates NOTCH pathway, and induces medulloblastoma in murine models." (PMID 39113693, 2024).
Obesity (8 papers, 2014 to 2023). Accumulation of substantial excess body fat. "In contrast to the characteristics of systemic BCL6 knockout mice, we found that hepatocyte-specific BCL6-deficient mice exhibited worse outcomes of HFD-induced obesity and hepatic steatosis." (PMID 35436984, 2022). "We discovered for the first time a BCL6/CD36 axis that centrally modulates obesity-associated NAFLD." (PMID 35436984, 2022). "The elucidation of the mechanisms that control Bcl6 expression could further clarify the underlying mechanisms of adipogenesis, thereby providing novel insights to prevent the growing incidence of obesity and metabolic syndromes in the modern world." (PMID 27251748, 2016). "Herein, we provide evidence that myeloid-CITED2 limits pro-inflammatory gene expression by elevating BCL6 signaling, and substantially curtails diet-induced obesity and insulin resistance." (PMID 37681868, 2023). "Our studies show that myeloid-CITED2 restrains diet-induced obesity, insulin resistance, and adipose tissue inflammation, and curtails broad pro-inflammatory gene expression by elevating BCL6 expression in macrophages." (PMID 37681868, 2023). "Collectively, our analyses uncover the pleiotropic nature of CITED2 which attenuates inflammation by promoting BCL6 expression in macrophages, and substantially curbs diet-induced obesity and insulin resistance in vivo." (PMID 37681868, 2023). "Overall, our findings highlight that CITED2 restrains inflammation by promoting BCL6 expression in macrophages, and limits diet-induced obesity and insulin resistance." (PMID 37681868, 2023). "In this study, we found that myeloid Cbp/p300-interacting transactivator with Glu/Asp-rich carboxy-terminal domain 2 (CITED2) promotes BCL6 signaling to limit the expression of inflammatory gene targets and the pathogenesis of diet-induced obesity and metabolic dysfunction." (PMID 37681868, 2023). "Bcl6 is essential for the differentiation and development of T follicular helper cells, suggesting that the decrease in T follicular helper cells might be involved in the functional imbalance of adipose tissue in obesity." (PMID 36313453, 2022). "It is important to understand whether and how Bcl6 might participate in regulating adipocyte function, since the central role of adipocytes in metabolic regulation is well recognized under physiological and pathological conditions such as obesity and diabetes." (PMID 24892698, 2014).
pancreatic cancer (8 papers, 2013 to 2024). "We used a panel of human lung, colorectal, and pancreatic cancer cell lines and examined the effects of BCL6 knockdown on their survival." (PMID 36377663, 2022). "FBXO11 was able to inhibit tumor cell growth and induced cell death by target BCL-6 for degradation, and deletion or mutation of FBXO11 in pancreatic cancer patients was associated with poor prognosis." (PMID 30341246, 2019). "Pancreatic cancer cells transiently expressing BCL-6 shRNA were significantly more invasive, while GW501516 treatment attenuated their invasive potential close to control levels." (PMID 23737761, 2013). "Our results show that PPARβ/δ activation by GW501516 suppresses expression of MMP-9 in human pancreatic cancer cells via BCL-6, with further inhibition on the ability of two cell lines, Miapaca-2 and BxPc-3, to invade a basement membrane." (PMID 23737761, 2013). "To determine if the PPARβ/δ/BCL-6 pathway is active in human pancreatic cancer cells, we used shRNA knock-down of PPARβ/δ and BCL-6 in conjunction with PPARβ/δ-specific activation by GW501516 to analyze the gene expression changes." (PMID 23737761, 2013). "Our results suggest, however, that BCL-6 and PPARβ/δ play critical roles in suppressing pro-migratory gene expression at the mRNA level and in ultimately controlling human pancreatic cancer cell invasion." (PMID 23737761, 2013). "We further evaluated two of these candidates by paired-end RNA-seq, from which we identified novel gene fusions, ATG7/RAF1 in pancreatic cancer and BCL6/RAF1 in anaplastic astrocytoma." (PMID 23637631, 2013). "Although several studies implicate PPARγ activation in inhibition of pancreatic cancer cell growth, little is known about the role of PPARβ/δ, save for its role in suppressing inflammation via BCL-6." (PMID 23737761, 2013). "In addition, GW501516-mediated activation of PPARβ/δ led to the reduced expression of MMP-9 after the BCL6 transcriptionnal repressor dissociation and consequently to the decrease of pancreatic cancer cell invasion capacities." (PMID 32519230, 2020). "Furthermore, we show that PPARβ/δ activation reduces Miapaca-2 and BxPc-3 invasion through a basement membrane, and that the transcriptional repressor BCL-6 plays a critical role in the pathway(s) regulating human pancreatic cancer cell invasion." (PMID 23737761, 2013). "Taken together, these results suggest that PPARβ/δ activation and subsequent suppression of proadhesion and pro-migratory genes via BCL-6 might prove useful in the control of pancreatic cancer." (PMID 23737761, 2013). "Besides, B cells could produce IL-35 in tumor regulates the unique transcriptional state of B cells and antagonizes plasma cell differentiation by stably expressing B-cell lineage-defining transcription factors Pax5 and Bcl6, to enable pancreatic tumor growth." (PMID 37505298, 2024). "Next, we examined BCL6 and KRAS-GTP protein expression in various human lung, colorectal, and pancreatic cancer cell lines and observed a positive correlation." (PMID 36377663, 2022). "In human pancreatic cancer tissue there was significantly higher expression of MMP-9 and PPARβ/δ, and lower levels of BCL-6 mRNA." (PMID 23737761, 2013). "Previous evidence, however, establishes a clear link between PPARβ/δ, BCL-6, and MMP-9, and we sought to elucidate the role(s) of PPARβ/δ activation on potential target genes involved in pancreatic cancer invasion and metastasis." (PMID 23737761, 2013). "Interestingly, DNA-chip hybridization assays identified both BCL-6 and BCL-10 as novel candidate genes in pancreatic cancer that were overexpressed in pancreatic cancer cell lines and primary tumor samples." (PMID 23737761, 2013). "As demonstrated in pancreatic cancer cells upon binding of GW501516, PPARβ/δ decreased TNFα (Tumor Necrosis Factor α)-induced NFκB activity leading to the induction of anti-inflammatory genes and consequently to the inhibition of pro-inflammatory genes through the dissociation of BCL6." (PMID 32519230, 2020).
pancreatic cancer (continued). "The PPARβ/δ-specific activator GW501516 and shRNAs to decrease expression of PPARβ/δ, BCL-6, and MMP-9 were used in two human pancreatic cancer cell lines, Miapaca-2 (COX-2 negative) and BxPc-3 (COX-2 positive)." (PMID 23737761, 2013).
prostate carcinoma (8 papers, 2015 to 2025). A carcinoma that arises from epithelial cells of the prostate gland. "Additionally, genetic mutations, including BRCA2, BCL6, CHEK2, and others, were also considered valuable predictors of BCR in prostate cancer." (PMID 40660132, 2025). "CNVs at this site may activate its nearby oncogenes such as ATR, BCL6 and PI3K family, leading to aggressive cancer hallmarks in prostate cancer." (PMID 38279874, 2024).
colitis (7 papers, 2020 to 2025). Inflammation of the colon. "Bcl6 inhibitor alleviated intestinal inflammation and reduced pro-inflammatory cytokines expression in mice with colitis." (PMID 40416976, 2025). "Our experimental results demonstrated that Bcl6 inhibitors significantly reduced the damage to intestinal epithelial cells and the secretion of inflammatory factors in colitis mice." (PMID 40416976, 2025). "In summary, this study demonstrated both in vivo and in vitro that the BCL6 inhibitor can alleviate acute colitis induced by DSS in mice." (PMID 40416976, 2025). "CCM can alleviate DSS-induced colitis in mice by modulating memory B cells and the Bcl-6-Syk-BLNK pathway." (PMID 38611938, 2024). "In the present study, the percentages of ICOS+, BCL-6+, PD-1+, and PD-L1+ Tfh cells were downregulated in the peripheral blood of colitis mice treated by SSP, while the number of Blimp-1+ Tfh cells was upregulated." (PMID 32581849, 2020). "This study investigated the effects of the BCL6 inhibitor FX1 on DSS-induced colitis in mice." (PMID 40416976, 2025). "However, our animal studies have indicated that Bcl6 possesses potential therapeutic effects on colitis." (PMID 40416976, 2025). "Furthermore, targeted inhibition of Bcl6 significantly alleviated colitis symptoms in these animals, as assessed by Disease Activity Index (DAI) scores and observed changes in the colon." (PMID 40416976, 2025). "Our findings demonstrate the efficacy of BCL6 inhibitor FX1 in treating colitis in mice." (PMID 40416976, 2025). "Bcl6 inhibitor alleviates inflammatory symptoms in mice with DSS induced acute colitis." (PMID 40416976, 2025). "Finally, to determine the consequences of elevated cytokine responses towards the microbiota in the context of Bcl6-deficiency, we exposed mice to dextran sulfate sodium (DSS)-induced colitis." (PMID 37950867, 2023). "One research showed that adoptive transfer of naive CD4+ T cells to Rag1−/− recipients will lead to development of colitis; however, adoptive transfer of naive Bcl6−/− CD4+ T cells into Rag1−/− recipient cannot induce Tfh cell differentiation and the development of colitis." (PMID 34471409, 2021). "The results indicated that SSP inhibited BCL-6/Blimp-1 signaling pathway in colitis mice." (PMID 32581849, 2020). "Deletion of Bcl6 results in dysregulation of the LTi-like ILC3 transcriptional program and markedly enhances expression of IL-17A and IL-17F in LTi-like ILC3, in a manner in part dependent upon the commensal microbiota - and associated with worsened inflammation in a model of colitis." (PMID 37950867, 2023). "Wild-type mice also had higher expression of genes associated with inflammatory cytokines (Il6 and Il22) and transcription factors downstream of both toll-like receptor and PAR2 signaling (Stat3 and Bcl6), compared to R38E-PAR2 mice after colitis." (PMID 39171684, 2024). "In the DSS colitis model, TLR4/MyD88 signaling consistently activates the IKK-NF-κB axis, thereby driving TNFα expression, potentially bypassing any inhibitory effects exerted by Bcl6." (PMID 40416976, 2025). "In contrast with mice in the DSS group, the numbers of CD4+CXCR5+ BCL-6+, CD4+CXCR5+ICOS+, and CD4+CXCR5+PD-1+ T cells were decreased, and CD4+CXCR5+Blimp-1+ T cells were significantly increased after colitis was treated with SSP and 5-ASA for 7 days." (PMID 32581849, 2020). "Through Western bolting assay, we verified the key proteins in the Bcl-6/Blimp-1 signaling pathway and found that SSP significantly inhibited expression of Bcl-6, STAT3, and p-STAT3 proteins and improved expression of Blimp-1 in colonic tissues of colitis mice." (PMID 32581849, 2020). "Compared with the normal group, the numbers of CD4+CXCR5+BCL-6+, CD4+CXCR5+ICOS+, CD4+CXCR5+PD-1+, and CD4+CXCR5+PD-L1+ T cells were significantly elevated, while CD4+CXCR5+Blimp-1+ T cells were inhibited in the peripheral blood of colitis mice in the DSS group." (PMID 32581849, 2020).